SLC3A1 (solute carrier family 3 member 1)
Diseases named in the same sentence as SLC3A1 in open-access papers (continued):
Sharing a sentence is not in itself a finding about the gene and the disease.
cystinuria (continued). "Cystinuria is well-suited for gene therapy, mainly because of the disease’s autosomal recessive nature and manageable gene sizes (SLC3A1 2.3 kb, SLC7A9 1.8 kb), also, the core of the pathogenic mechanisms is located in the proximal tubule, which is easily accessible." (PMID 40786091, 2025). "SLC3A1 gene mutations and deletions were associated with cystinuria." (PMID 39026605, 2024). "To date, two genes have been identified to cause cystinuria: SLC3A1 and SLC7A9." (PMID 37893120, 2023). "However, a homozygous nonsense mutation c.1113C> A (p.Tyr371*) in the SLC3A1 gene was detected, which is the pathogenic gene that causes cystinuria." (PMID 37525149, 2023). "According to previous studies, pathogenic variants in the SLC3A1 gene can cause cystinuria." (PMID 37525149, 2023). "SLC3A1 gene is a protein-coding gene associated with the transportation of amino acids in the renal tubule and intestinal tract, and aberrations in this gene have been associated with cystinuria, a metabolic disorder of the kidneys, bladder, and ureter." (PMID 37669321, 2023). "In 1994, pathogenic variants of the SLC3A1 gene were identified as leading to cystinuria." (PMID 38114997, 2023). "Therefore, we performed genetic analysis of a peripheral blood sample, which revealed a SLC3A1 gene mutation known to be a pathogenic variant of cystinuria." (PMID 37525149, 2023). "In addition, as patients with cystinuria mutations in the SLC3A1 gene have impaired the assembly of both cystine transporters, these patients were grouped without considering SLC7A13 variants." (PMID 38138969, 2023). "Cystinuria can be caused by mutations in the SLC3A1 and/or SLC7A9 gene." (PMID 38114997, 2023). "Due to the limited number of cystinuria cases reported and analyzed in China, the correlation between SLC3A1 mutation pattern and clinical presentation remains unclear." (PMID 38114997, 2023). "Our study identified a novel heterozygous mutation of SLC3A1 for cystinuria based on WES screening of a 5-year-old case and indicated that a gene-mutation-based screening strategy should be considered in the clinic to provide a promising approach for cystine stone diagnosis and clinical management." (PMID 36421847, 2022). "Thus, researchers concluded that SLC3A1 causes cystinuria, while PREPL likely causes the remaining phenotypic features." (PMID 36313552, 2022). "Likewise, in the SLC3A1 gene responsible for encoding rBAT, more than 128 mutations have been identified, of which 93 have been described as causing cystinuria where one of the most frequent is the T216M SNP (rs369641941)." (PMID 33007934, 2020). "Homozygous and heterozygous SLC3A1 mutations lead to cystinuria (OMIM # 220100)." (PMID 32707643, 2020). "Cystinuria is a metabolic disease caused by defects in the SLC3A1 and SLC7A9 genes." (PMID 32133030, 2020). "Cystinuria caused by mutations in SLC3A1 (Type A) is an autosomal recessive condition." (PMID 33262960, 2020). "In 103 cystinuria patients, 83.5% had at least one SLC3A1 or SLC7A9 mutation." (PMID 30342472, 2018). "Cystinuria (OMIM #220100) is an inherited autosomal recessive aminoaciduria due to pathogenic variants in the SLC3A1 (solute carrier family 3 member 1 OMIM #104614) or SLC7A9 (solute carrier family 7 member 9 OMIM # 604144) genes, encoding respectively for rBAT and b0, +AT." (PMID 28717662, 2017). "Cystinuria is associated with mutations in SLC3A1 and SLC7A9 genes." (PMID 25029527, 2014). "However, in the case of clinical diagnosis of cystinuria, the identification of only one mutation in SLC3A1 should be sufficient for confirmation." (PMID 22480232, 2012). "Furthermore, it can be asked whether the detection of only one mutated allele in SLC3A1 or SLC7A9 is indeed sufficient to explain the cystinuria phenotype, or whether a second genomic variant in the same or another gene is required." (PMID 30342472, 2018).
cystinuria (continued). "Additionally, we found that the frequency of ExAC variants was higher for SLC3A1, which may represent the autosomal recessive inheritance of cystinuria when caused by SLC3A1 mutations." (PMID 28812535, 2017). "The amino acid substitution p.Thr216Met in exon 3 is the second frequent variant (~13% of all identified SLC3A1 alleles), but it shows a preponderance in patients from South-Eastern Europe (for review:) and thus reflects the effect of the ethnic origin on the distribution of cystinuria mutations." (PMID 22480232, 2012). "Both type A (SLC3A1 mutations) and type B (SLC7A9 mutations) cystinuria share similar clinical courses, though males tend to experience more severe disease." (PMID 41142409, 2025). "Cystinuria is a rare autosomal recessive disorder affecting SLC3A1 or SLC7A9 genes, promoting increased urine cystine excretion favoring crystal precipitation within the distal tubules and subsequent formation of cystine stones." (PMID 41333668, 2025). "Our studies uncover the crucial role of Slc3a1 in mitochondrial functions and provide novel insights into potential interventions for sexual dimorphism of cystinuria." (PMID 40110490, 2025). "Recent studies have identified a critical mitochondrial function for the SLC3A1 gene in regulating these sex differences in cystinuria." (PMID 41142409, 2025). "Taken together, these findings indicate that Slc3a1 KO male mice display a more pronounced cystinuria phenotype and renal injury than their female counterparts." (PMID 40110490, 2025). "Further investigations revealed aberrant mitochondrial functions as the primary factor contributing to the severity of cystinuria in Slc3a1 knockout male mice." (PMID 40110490, 2025). "Initially, we examined the changes in mitochondrial biogenetic markers between WT and Slc3a1 KO mice of the same sex to confirm the involvement of mitochondria in cystinuria." (PMID 40110490, 2025). "Four cystinuria patients had a monoallelic P/LP pathogenic mutation, two in the SLC3A1 and two in the SLC7A9 genes, all of them presenting manifestations of cystinuria." (PMID 40428323, 2025). "This mitochondrial function of SLC3A1 broadens the understanding of cystinuria beyond amino acid transport defects, implicating mitochondrial impairment and oxidative stress as key contributors to stone formation and disease severity, especially in males." (PMID 41142409, 2025). "We detected biallelic pathogenic variants in SLC3A1 for two patients (type A cystinuria) and biallelic pathogenic and likely pathogenic variants in SLC7A9 for another two patients (type B cystinuria)." (PMID 40428323, 2025). "Cystinuria results from variants in SLC3A1 and SLC7A9, which encode for solute carrier family 3 member 1 and solute carrier family 7 member 9, respectively, both of which are expressed in the PT." (PMID 38606357, 2024). "A novel predicted target of miR-29b is the cystine transporter SLC3A1; this interaction was revealed in cystinuria patients." (PMID 39026605, 2024). "The defective SLC7A9 and SLC3A1 will lead to cystinuria, characterized by defective cystine and dibasic amino acid transport across the apical membrane of epithelial cells of the small intestine and the renal proximal tubules." (PMID 39259834, 2024). "We also recorded the patient’s clinical characteristics and treatments to enhance our understanding of the link between the SLC3A1 genotype and the manifestations of cystinuria in the Chinese population." (PMID 38114997, 2023). "Genetic variants in the SLC3A1 and SLC7A9 genes underlie cystinuria, as they encode the heavy (rBAT) and the light (b0,+AT) subunits of the cystine and dibasic amino acid transport system b0,+." (PMID 38138969, 2023). "More than 20 years have passed since the identification of SLC3A1 and SLC7A9 as causative genes for cystinuria." (PMID 38138969, 2023). "First, the SLC3A1 and SLC7A9 genes were screened for cystinuria-causing mutations in the 34 patients recruited for this study." (PMID 38138969, 2023).
cystinuria (continued). "In 2002, the International Cystinuria Consortium classified cystinuria based on mutations in different genes into type A (SLC3A1 mutations), type B (SLC7A9 mutations) and type AB (both the SLC3A1 and SLC7A9 mutations)." (PMID 38114997, 2023). "A further study of new families presenting with cystinuria-hypotonia found that in some patients only SLC3A1 and PREPL were deleted, while PPM1B and C2orf34 remained unaffected." (PMID 36313552, 2022). "Mutations in the rBAT heavy subunit coding gene (SLC3A1) or the b0,+AT light subunit coding gene (SLC7A9) underlie Cystinuria, the most common inherited form of kidney stones, with a worldwide prevalence of 1:7000." (PMID 35209204, 2022). "To conclude, our study expands the phenotypic and genotypic spectrum of SLC3A1 and indicates that genetic screening should be considered in the clinic to provide more effective and precise treatment for cystinuria." (PMID 36421847, 2022). "To gain insight into the cystine stone development process, we applied longitudinal μCT scanning to characterize early stone formation and initiation in a mouse model of cystinuria (Slc3a1-/-)." (PMID 35771811, 2022). "Cystinuria can be categorized into three types: SLC3A1 mutation is known as type A; SLC7A9 mutation is known as type B; both SLC3A1 and SLC7A9 mutations are known as type AB." (PMID 36421847, 2022). "In Australian Cattle dogs with cystinuria, a heterozygous deletion of six bases was found in exon 6 of the SLC3A1 gene." (PMID 34438894, 2021). "We have previously reported 57 mutations in one of two genes (SLC3A1 and SLC7A9) in a large UK cohort of cystinuria patients." (PMID 33169184, 2021). "In humans a deletion of the 2p21 region including four genes (PP2Cβ, SLC3A1, PREPL and CAMKMT) was described as a syndrome (MIM #606,407) associated with cystinuria, intellectual disability, mitochondrial disease, hypotonia and facial dysmorphism." (PMID 31865460, 2020). "In fact, we identified in two patients (AMS and BDA) biallelic likely pathogenic variants in two genes (SLC3A1, LRP2) whose mutations are known to cause cystinuria and DB/FOAR." (PMID 31947599, 2020). "Knockout mice for PREPL suffer neonatal hypotonia and diminished growth making this gene a less likely candidate, similarly to SLC3A1 null mice displaying cystinuria." (PMID 31865460, 2020). "SLC3A1 exit from the endoplasmic reticulum is facilitated by SLC7A9, and mutations in SLC7A9 also result in cystinuria." (PMID 31100816, 2019). "In the SNP SLC3A1, we found a predominance of the heterozygote genotype for cystinuria and control patients." (PMID 30450686, 2019). "With the exclusion of SLC7A13/AGT1 as the third cystinuria gene, the question remains unanswered why analysis for the two cystinuria genes SLC3A1 and SLC7A9 succeeds only in up to 85%." (PMID 30342472, 2018). "Using a literature search, we collated a set of 94 SLC3A1 and 58 SLC7A9 point mutations known to be associated with cystinuria." (PMID 28812535, 2017). "The results of this study are promising and highlight the areas of research which must now be pursued to better understand how mutations in SLC3A1 and SLC7A9 cause cystinuria." (PMID 28812535, 2017). "From the clinical studies we identified a total of 94 SLC3A1 and 58 SLC7A9 cystinuria associated point mutations." (PMID 28812535, 2017). "Across 49 studies, 58 and 94 cystinuria associated point mutations were identified in SLC7A9 and SLC3A1, respectively." (PMID 28812535, 2017). "Cystinuria can be inherited in humans as an autosomal recessive (type IA and IB) and dominant (type IIA and IIB) trait due to SLC3A1 (IA and IIA) and SLC7A9 (IB and IIB) variants, respectively." (PMID 27404572, 2016). "Summarizing, generation and characterization of type AB cystinuria mouse model exhibited a digenic inheritance where 4% of double heterozygous mice (Slc7a9+/-Slc3a1+/-) present lithiasis phenotype." (PMID 26359869, 2015).
cystinuria (continued). "Cystinuria is an inherited aminoaciduria caused by mutations in SLC7A9 and SLC3A1 that encode for the two subunits b0,+AT and rBAT, respectively." (PMID 26359869, 2015). "Tracking the lithiasic phenotype by X-ray allowed us to detect calculi formation in 4% of the double heterozygous mice (Slc7a9+/-Slc3a1+/-) demonstrating that cystinuria has a digenic inheritance pattern in this mouse model." (PMID 26359869, 2015). "Heterozygosity for the 6 bp deletion in the SLC3A1 gene was associated with cystinuria in intact male AUCDs, but not in females." (PMID 41600767, 2026). "Mutations in the SLC3A1 and SLC7A9 genes lead to cystinuria, a hereditary disorder characterized by defective reabsorption of cystine and dibasic amino acids (lysine, arginine, and ornithine) in the kidney and intestine, resulting in recurrent cystine kidney stones." (PMID 41142409, 2025). "To investigate whether androgens contribute to the sexual dimorphisms of cystinuria, we performed orchiectomy on Slc3a1 KO male mice at 3 weeks old and sacrificed them at 20 weeks old." (PMID 40110490, 2025). "Considering that the tested Slc7a13 and orchidectomy were not the underlying causes of sex differences in cystinuria, we conducted a bulk RNA sequencing on six Slc3a1 KO kidney samples (3 males and 3 females) to further investigate the underlying mechanism." (PMID 40110490, 2025). "Furthermore, MS increased the metabolites related to cystinuria, which is caused by defective in amino acid transporter, such as SLC7A9 and SLC3A1." (PMID 39259834, 2024). "This could be due to overexpression of upstream miR-29b as SLC3A1 is reported as a predicted miR-29b target in TargetScan database, and this interaction was evidenced in cystinuria patients." (PMID 39026605, 2024). "We identified two heterozygous mutations (c.898_905del and c.1898_1899insAT) in SLC3A1; one of which has not been described in other cystinuria patients." (PMID 38114997, 2023). "Variants in SLC3A1 and SLC7A9 follow autosomal recessive inheritance and autosomal dominant inheritance with reduced penetrance, respectively, which complicates the interpretation of cystinuria-related variants." (PMID 37439839, 2023). "To date, two genes, SLC3A1 and SLC7A9, have been identified as causes of cystinuria." (PMID 37893120, 2023). "The two patients with a definite diagnosis of cystinuria, due to detection of variations in the SLC3A1 and SLC7A9 genes and stone analysis suggesting l-cystine, were treated with strict alkalization urine therapy because they were too young to develop a typical staghorn stone." (PMID 35612621, 2022). "Two genes have been identified to be involved in cystinuria formation, i.e., SLC3A1 and SLC7A9." (PMID 36421847, 2022). "Finally, it is also worth mentioning that cells carrying p.(Val523del) mutation downregulate SLC3A1 gene, which codifies for the amino acid transporter ATR1 that is mutated in patients affected of cystinuria." (PMID 33987651, 2021). "a low rate of SLC3A1 mutation in cystinuria likely was due to lack of screening for alternative isoform sequences that play a role in the renal transport system." (PMID 34612606, 2021). "An SLC3A1 nonsense mutation appears to be associated with cystinuria in Mastiffs and related breeds, but not in Irish Terriers or Scottish Deerhounds." (PMID 34438894, 2021). "Mean HU was compared for both cystinuria genes (SLC3A1 and SLC7A9) using an independent t-test." (PMID 33169184, 2021). "In two adults patients (AMS and BDA), we detected biallelic likely pathogenic variants in SLC3A1 and LRP2 genes whose mutations are responsible for the recessive diseases Cystinuria (MIM#220100) and Donnai–Barrow/Facio-oculo-acoustico-renal syndrome (DB/FOAR, MIM#222448), respectively." (PMID 31947599, 2020). "We screened a cohort of 17 cystinuria patients for SLC7A13 variants which were negative for SLC3A1 and SLC7A9 mutations." (PMID 30342472, 2018).
cystinuria (continued). "Many mutations have been identified in both SLC3A1 and SLC7A9 in individuals with cystinuria." (PMID 28812535, 2017). "Importantly, this study shows how the experimental assessment of the impact on splicing of SLC3A1 and SLC7A9 variants contributed to the full molecular characterization of cystinuria." (PMID 28717662, 2017). "The variant identified in SLC3A1 has already been described in patients with cystinuria (#220100), but according to their phenotypes this variant cannot explain case 1 phenotype, that is why SLC3A1 was excluded as causative gene." (PMID 28800606, 2017). "rBAT is coded by rBAT / SLC3A1 which is well known as the responsible gene of type I cystinuria." (PMID 26318292, 2015). "Two different types of cystinuria may be distinguished according to genetic: type A cystinuria, due to mutations along the SLC3A1 gene encoding the rBAT heavy subunit and type B cystinuria, with mutations in the SLC7A9 gene encoding for light subunit b0,+ AT." (PMID 25048459, 2014). "A more recent classification system has been developed, which designates patients who are homozygous for the SLC3A1 mutations as cystinuria type A, patients who are homozygous for the SLC7A9 mutations as type B, and those who have a mutation in both the SLC3A1 and SLC7A9 genes as type AB." (PMID 22857835, 2012). "We wondered whether the sex-dependent expression of Slc7a13 was the cause of the sex differences of Slc3a1 KO induced cystinuria, thus we generated Slc7a13 KO mice with CRISPR/Cas9 technology and crossed them with Slc3a1 KO mice to make a double KO (DKO) mouse." (PMID 40110490, 2025). "To date, a total of 210 clinical mutations of SLC3A1 have been documented by the Human Gene Mutation Database (HGMD), and genetic diversity of the population has been reported in different ethnic groups, indicating substantial heterogeneity in the genetic basis of cystinuria." (PMID 36421847, 2022). "In dogs, cystinuria had been historically divided into two types: type I referring to a mutation in a SLC3A1 gene with autosomal recessive inheritance and non-type I cystinuria which is associated with milder degree of cystinuria and which is observed in mature intact males of various breeds." (PMID 34438894, 2021). "It has yet to be determined if SLC7A13 mutations could help explain the isolated cystinuria observed in patients who still do not have any detectable mutation in SLC3A1 and SLC7A9." (PMID 31878022, 2019). "Thus, no new SLC3A1 variants causing cystinuria in cats were discovered among the cats studied here." (PMID 27404572, 2016). "The involvement of the SLC3A1 (OMIM 104614) gene in the aetiology of cystinuria could be established in 1994 by establishing linkage of the disease to 2p and by identifying the first mutations in cystinuria patients." (PMID 22480232, 2012). "After identification of the molecular basis of the disease a new classification was suggested: the autosomal recessively inherited type I cystinuria which is mainly caused by SLC3A1 mutations, and the incomplete autosomal dominant non-type I cystinuria associated with SLC7A9 variants." (PMID 22480232, 2012). "Further genetic linkage studies indicated that not all cystinuria families were caused by SLC3A1 defects, and the second cystinuria gene could be localised to chromosome 19q13." (PMID 22480232, 2012). "In human patients cystinuria is attended by mutations in SLC3A1 and SLC7A9, but it is not known whether these defects are present in carriers of HNF1β mutation." (PMID 22438943, 2012). "Homozygous deletion of both PREPL and the neighboring gene SLC3A1 result in Hypotonia-cystinuria syndrome (AR inheritance, OMIM phenotype number 606407) with hypotonia, cystinuria, and cystine NL." (PMID 38606357, 2024). "In our study, SLC3A1, SLC7A9, and SLC7A13 genes were sequenced in 34 clinically diagnosed cystinuria patients." (PMID 38138969, 2023).